FOXP3 (forkhead box P3)
Diseases named in the same sentence as FOXP3 in open-access papers (continued):
Sharing a sentence is not in itself a finding about the gene and the disease.
lymphoma (continued). "Our data suggested that CD8+ Tfr cells might engage with lymphoma B cells and DCs via ICOS/ICOSL interactions, potentially stabilising FOXP3 function but also increasing IL‐10 production by Tregs, enhancing suppressive potency." (PMID 41190308, 2025). "For instance, the induction of FoxP3+ regulatory T-cells through TGF-β1 by PSGs could impair antitumor immunity, a mechanism relevant in leukemias and lymphomas where immune evasion plays a key role." (PMID 40806565, 2025). "FoxP3+ cells were detected in the TME of all analyzed samples (n = 101) in varying numbers, except for four PTCL-NOS cases (HTLV-1-negative) that expressed FoxP3 in the lymphoma cells." (PMID 39682197, 2024). "Since nTFHLs are not derived from Tregs, unlike ATLL and some rare PTCL-NOS cases, the lymphoma cells in these subtypes are not expected to express FoxP3." (PMID 39682197, 2024). "The expression of FoxP3+ in lymphoma cells in peripheral T-cell lymphomas not otherwise specified (PTCLs-NOS) (HTLV-1 negative) is extremely rare." (PMID 39682197, 2024). "The percentage of FOXP3+ T-regulatory cells was <10% in seven cases, 10-25% in five cases, >25% in two cases, and non-evaluable in two cases, due to exhaustion of the lymphoma tissue." (PMID 37900389, 2023). "CD4+CD25+ FOXP3+CD127low Tregs are markedly increased in peripheral blood mononuclear cells (PBMCs) versus healthy controls regardless of lymphoma subtype, and correlated with disease stage and serum lactate dehydrogenase." (PMID 22151904, 2011). "T-lymphocytes—including CD4+ T-helper cells (Ths), CD4+/FOXP3+ regulatory T-cells (Tregs), and CD8+ cytotoxic T-lymphocytes (CTLs)—are fundamental for immune surveillance and disease progression and, thus, continue to be studied extensively in essentially all lymphoma subtypes." (PMID 33804869, 2021). "In this study, we demonstrated an elevated frequency of CD4+CD25+FoxP3+CD127lo Treg in PB, BM and involved lymphatic tissues from patients with B-cell NHL, and we also showed that these cells could be potently induced by lymphoma B cells in vitro." (PMID 22174855, 2011). "The prognostic potential of FoxP3+ Tregs and their varying numbers in the TME has attracted substantial interest, especially in relation to different lymphoma subtypes from which positive and negative prognostic effects have been reported." (PMID 39682197, 2024). "In contrast with the lymphoma models, ICBs-CT26 treatment did not induce changes in classical CD8+ nor CD4+ populations, however did induce significant increase of CD4+CD25+FoXP3 and CD4+ Tbet+ subpopulation in the spleen, without changes in CD4+ROR-γt+ subpopulations." (PMID 33623783, 2021). "Notably, the presence of FoxP3+ Tregs within the TME of nTFHLs follicular type (nTFHLs-F), nTFHLs not otherwise specified (nTFHL-NOS), and composite lymphomas (CLs; nTFHL-AI and diffuse large B-cell lymphomas (DLBCLs) or marginal zone lymphomas (MZLs)) remains unexplored." (PMID 39682197, 2024).
malaria (54 papers, 2009 to 2025). Malaria is a serious and sometimes fatal disease caused by a parasite that commonly infects a certain type of mosquito which feeds on humans. "Here, we show examples for Tr1 identification using IL-10 Foxp3 double reporter mice in the small intestine under steady-state conditions, and in a mouse model of malaria, a disease well known to be associated with Tr1 cells both in mouse and human." (PMID 34910301, 2021). "Therapeutically, LD01 treatment of mice infected with a lethal malaria strain resulted in survival that was associated with lower numbers of FOXP3+Tbet+CD4+ regulatory T cells." (PMID 32733457, 2020). "Previous studies have demonstrated that FoxP3 gene polymorphisms associated with human diseases such as malaria, hepatitis B-related hepatocellular carcinoma, autoimmune diseases, IPEX syndrome, preeclampsia, abortion and cancer." (PMID 29020928, 2017). "Another potential mechanism for the observed decline in Tregs among children chronically exposed to malaria is via loss of FOXP3 expression by “unstable” Tregs, which has been reported to occur in highly inflammatory immune environments." (PMID 26182204, 2015). "The study indicated that the STAT6 promoter polymorphism rs3024944 was associated with uncomplicated malaria, whereas the FOXP3 promoter variant rs11091253 was associated with significant P. falciparum parasitaemia levels." (PMID 23297791, 2013). "Interleukin-2 (IL-2), a pro-inflammatory cytokine implicated in malaria pathogenesis has also been shown to be a key regulator of Foxp3." (PMID 21439091, 2011). "Therefore, possible involvement of the ICOS dependent regulatory CD4+ICOS+Foxp3+ T cells in resistance/susceptibility during malaria parasite is explored in this study." (PMID 35109868, 2022). "Indeed, higher blood parasitemia levels are associated with higher frequencies of CD4+Foxp3+ Tregs in humans and mice with malaria." (PMID 30915078, 2019). "So far, little information is available about FoxP3 gene polymorphism in tuberculosis, but two studies reported that FoxP3 gene polymorphism may be associated with hepatitis B-related and malaria." (PMID 29020928, 2017). "The progressive decline in circulating Tregs in children heavily exposed to malaria could be explained by changes in Treg homeostasis such as decreased induction, increased loss (due to apoptosis or downregulation of FOXP3), or both." (PMID 26182204, 2015). "A study carried out in Fulani, a West African ethnic group with low susceptibility to malaria, reported that this population’s PBMCs express higher amounts of RNA for several Th1 and Th2 related genes but gene expression of FOXP3 and cytotoxic T lymphocyte antigen 4 (CTLA4) was markedly lower." (PMID 24642188, 2014). "A functional deficit of Treg cells, characterized by reduced expression of CTLA-4 (cytotoxic T lymphocyte antigen 4) and FoxP3 (forkhead box P3 transcription factor), was observed in studies involving the Fulani ethnic group that present low susceptibility to clinical malaria by P. falciparum." (PMID 20224778, 2010). "Interestingly, high FOXP3 mRNA levels at base line were found to be associated with reduced parasite-specific IFN-γ memory responses amongst PBMCs collected form convalescent malaria patients." (PMID 20442856, 2010). "Although it is likely that increased FoxP3 expression in our study is linked to natural exposure to parasite further studies are warranted to exclude the possibility of the effect being exacerbated by malaria vaccination." (PMID 20037644, 2009). "Consistent with the emergence of Tr1 cells from Th1 subsets, the majority of Tr1 cells where Th1-like (CXCR3+/CCR6-/CXCR5-/FoxP3-) at day 0 during malaria (median 65.4%, IQR 62.5-73.8%)." (PMID 37968278, 2023).
malaria (continued). "Upon intracellular staining of Foxp3, it was found that infection with lethal malaria parasite induced significantly higher frequencies of CD4+ICOS+Foxp3+Treg cells with nearly 50% of CD4+ICOS+ T cells expressed Foxp3 by day 10th post infection." (PMID 35109868, 2022). "Plasma cytokine levels were measured in 80 patients with severe anaemic malaria and 186 with a mild presentation using ELISA, and rtPCR was used to measure FOXP3 mRNA expression." (PMID 36293524, 2022). "Reporter mice for IL-10 (eGFP) and FOXP3 (RFP) were infected by intraperitoneal injection of 1 × 105Plasmodium berghei ANKA parasites, one of the causative agents of malaria in mice." (PMID 34910301, 2021). "In malaria-endemic areas, Treg expressing FoxP3 are correlated with higher parasitemia and lower pro-inflammatory responses and lower numbers are associated with better disease outcome." (PMID 34684226, 2021). "Relative researches found that the maintenance of CD25+Foxp3+ cells required IL-2 assist critically in malaria." (PMID 32252652, 2020). "Intriguingly, we found that LD01 treatment of mice in the lethal malaria model significantly reduced the numbers of splenic FOXP3+Tbet+CD4+ Tregs compared to anti-PD1 mAb-treated mice." (PMID 32733457, 2020). "Our group recently used the P. yoelli 17XNL model of infection to show that CD4+ Foxp3+ Tregs expand during a specific temporal window of blood-stage malaria." (PMID 32043415, 2020). "In this study, the positive correlation observed between FOXP3 and PD-1 T cells as well as between PD-1 and PD-1CTLA4 T cells could indicate that these markers play complementary roles in mediating the increasing immune activation that is associated with symptomatic malaria." (PMID 31316497, 2019). "Of note, malaria patients also showed a higher percentage of Foxp3+CD4+ Tregs than healthy controls but frequencies of Foxp3+ Tregs and PD1+CTLA4+ CD4+ T cells did not correlate." (PMID 27802341, 2016). "In utero exposure to malaria has been reported to induce numerous immunoregulatory mechanisms in the fetus, including expansion of FoxP3+ T regulatory cells, increased levels of suppressive cytokines such as IL-10 and TGF-β and diminished CD4 Th1 responses." (PMID 27717402, 2016). "IL-10 in response to EBNA1 was also produced within the CD4+ T cell Foxp3- populations in contrast to the malaria antigen, PfSEA-1 that only stimulated IL-10 from Foxp3+ Tregs." (PMID 28033393, 2016). "We found that both the frequency and absolute numbers of FoxP3+ Tregs in peripheral blood declined markedly with increasing prior malaria incidence." (PMID 26182204, 2015). "Tregs were associated with risk of malaria disease: reduced expression of CTLA-4 and FOXP3 was found in Fulani, an ethnic group in Burkina Faso relatively resistant to P. falciparum compared to Mossi (a different ethnic group from the same region)." (PMID 26029205, 2015). "Here, we have shown through both cross-sectional and longitudinal studies that the percentage and absolute number of FoxP3+ Tregs in peripheral blood are influenced by repeated exposure to malaria." (PMID 26182204, 2015). "In prior studies, FOXP3 mRNA levels measured during acute malaria were shown to correlate inversely with the magnitude of the subsequent Th1 memory response to P. falciparum measured 28 days after infection." (PMID 26182204, 2015). "Together these data demonstrate that the impact of chronic malaria antigen exposure on the FoxP3+ regulatory T cell population is quite different from that of acute infection of malaria-naïve individuals." (PMID 26182204, 2015). "FOXP3 mRNA levels in children with acute malaria have been shown to correlate inversely with the magnitude of the subsequent Th1 memory response to P. falciparum measured 28 days after infection." (PMID 26182204, 2015).
malaria (continued). "We assessed transcription factor expression within the dominant population of malaria-specific IFNγ/IL-10 co-producing cells and found that these cells uniformly were TBet+ and FoxP3−." (PMID 24415936, 2014). "To summarize, selected regulatory SNPs in the promoter region of FOXP3, IL10RA, IL10RB, STAT6 and TNFRSF18 genes have been investigated for possible association with uncomplicated malaria and high P. falciparum parasite density among Congolese children." (PMID 23297791, 2013). "The induction of CD4+CD25+Foxp3+ regulatory T cells (Tregs) by malaria parasites has been described and is related to the ability of parasites to escape from both protective and harmful host immunity, especially concerning splenic T cells response." (PMID 23646169, 2013). "Although the role of Foxp3+ Treg during malaria is far from clear, Foxp3+ Treg can, in other models, regulate Th1 cell homeostasis." (PMID 23593003, 2013). "In this paper, the frequencies of the T cells CD4+CD25+FoxP3+ subsets were similar in Fulani and Mossi ethnic groups at the low and high malaria transmission period." (PMID 22283984, 2012). "Studies in malaria patients indicate that higher frequencies of peripheral blood CD4+ Foxp3+ CD25+ regulatory T (Treg) cells correlate with increased blood parasitemia." (PMID 21170302, 2010). "Others have shown that elevated levels of FoxP3 expressing regulatory T cells are found in malaria infected patients." (PMID 20037644, 2009). "The importance of early TGFβ exposure for Foxp3 induction has been shown in vitro and in experimentally malaria-infected human volunteers." (PMID 19680449, 2009). "A subset of TNFRII+ Treg cells with high expression of Foxp3 was increased in severe relative to uncomplicated malaria." (PMID 19390618, 2009). "In summary, we examined and defined the contribution of host immune mechanisms including APC-mediated TCR stimulation and cytokines to the induction of Foxp3 expression by the malaria parasite." (PMID 19680449, 2009). "CD4+CD25+Foxp3+CD127lo Treg cells were significantly elevated in patients with uncomplicated (UM; n = 17) and severe malaria (SM; n = 16) relative to exposed asymptomatic controls (AC; n = 10)." (PMID 19390618, 2009). "In this study we investigated the role of commonly accepted factors for Foxp3 induction, TCR stimulation and cytokines such as IL-2, TGFβ and IL-10, in the generation of human CD4+CD25+Foxp3+ T cells by the malaria parasite Plasmodium falciparum." (PMID 19680449, 2009). "Regulatory T (Treg) cells, characterized by FOXP3 expression, modulate immune responses in malaria." (PMID 40523953, 2025). "This could contribute to the observed upregulation of FOXP3 mRNA in mild malaria since TGF-β and IL-9 both contribute to Treg upregulation." (PMID 36293524, 2022). "A study examining regulatory gene variants in Congo showed a disparate response with STAT6 and FOXP3 among malaria-infected children, with the STAT6 promoter variant rs3024944 being associated with uncomplicated malaria, and the FOXP3 SNP rs11091253 being associated with parasitemia." (PMID 31979279, 2020). "Together, our findings indicate Th1-like CD4+T-bet+Foxp3+ Tregs that express CXCR3 are induced during acute blood-stage malaria and suggest CXCR3 expression on CD4+ Th1 cells may contribute to their migration to the spleen." (PMID 30915078, 2019). "Foxp3+ regulatory T cells (Tregs) are also crucial to protect the host from immunopathology and severe disease, but these cells can suppress protective immune responses to malaria." (PMID 30915078, 2019). "In addition to CD4+ Th1 and Tfh cells, Foxp3+ Tregs play an important regulatory role during malaria as a counterbalance to control excessive pro-inflammatory responses and limit immunopathology." (PMID 30915078, 2019). "Prior studies that used less precise definitions (e.g., without assessing expression of transcription factor FoxP3) found associations with in utero malaria exposure." (PMID 27717402, 2016).
malaria (continued). "In this context, a role for Foxp3+ CD4+ regulatory T cells (Tregs) as well as non-Foxp3+ activated/memory (CD45RO+) CD4+ T cells in regulating malaria-induced inflammation and subsequent immunopathology is supported by many studies in human patients and in surrogate mouse models." (PMID 27792766, 2016). "In rural Gambia, the percentage and absolute count of FoxP3+CD127low CD4 T cells were shown to increase following the malaria transmission season, and are significantly higher among malaria-exposed rural Gambians than among ethnically matched urban Gambians with no malaria exposure." (PMID 26182204, 2015). "Similarly, FOXP3 expression among malaria-naive adults following experimental sporozoite vaccination correlates inversely with the subsequent Th1 memory response." (PMID 26182204, 2015). "Similarly, FOXP3 expression among malaria-naive adults following experimental sporozoite vaccination was shown to correlate inversely with the Th1 memory response measured >100 days later." (PMID 26182204, 2015). "However, we found some cases of P. vivax-infected patients and uninfected malaria-exposed controls that had high levels of FOXP3+ Treg cells." (PMID 23049909, 2012). "The majority of CD4+ CD25high cells were found to express Foxp3, suggesting that natural Treg cells may negatively affect natural acquired immunity to malaria." (PMID 20442856, 2010). "Interestingly and in line with our findings, Treg frequencies determined by Foxp3 mRNA levels were recently shown to negatively correlate with the magnitude of malaria-specific memory IFNγ responses in human malaria patients." (PMID 19680449, 2009). "Regulatory T cells (Tregs) expressing the transcription factor Foxp3, which drives genes involved in immunosuppression, are specialized immune cells that can inhibit both protective and harmful inflammatory responses during malaria." (PMID 19680449, 2009). "To test whether TGFβ plays a role in the induction of Foxp3+ CD4 T cells by malaria-infected RBCs, we added TGFβ-neutralizing antibody to the iRBC∶PBMC co-culture." (PMID 19680449, 2009). "We first asked whether Foxp3 expressing CD4 T cells could be induced by culturing PBMCs of healthy Australian blood bank donors with malaria-infected trophozoite stage RBCs (iRBCs)." (PMID 19680449, 2009). "Therefore, in vitro assays reflecting in vivo processes as closely as possible are needed to examine the mechanisms involved in the malaria parasite-mediated generation of CD4+CD25+Foxp3+ human T cells." (PMID 19680449, 2009). "Foxp3+ Tregs have ubiquitous roles in anti-malarial immunity in both mice and humans, yet owing to the pleiotropic effect of these cells and the complexity of anti-malaria immunity, the full contribution of these cells to protection and pathology during malaria is not fully understood." (PMID 37824458, 2023). "Independent support for TGF-β promoting Treg development during malaria comes from in vitro studies in which co-culture of human peripheral blood mononuclear cells and RBCs infected with P. falciparum induced development of FoxP3-expressing Tregs, with TGF-β required for production of FoxP3hi Tregs." (PMID 32043415, 2020). "In summary, our data indicate that classical FOXP3+ Tregs are unable to control the florid inflammation that accompanies acute malaria infections and this component of the immunoregulatory arsenal is rapidly overwhelmed in children with either mild or severe malaria." (PMID 19343213, 2009). "Another study reported that during the blood stage of malaria, the parasite induces CD4+Foxp3+CD25+ regulatory T cells to release a fibrinogen-like protein 2 (sFGL2), resulting in immunosuppression, thereby enhancing the infection." (PMID 37219610, 2023). "A stringent definition of T regulatory cells was used, defined as CD25+FoxP3+CD127lo/− CD4 T cells, and compared in utero malaria exposed and unexposed infants." (PMID 27717402, 2016).